MAPK7 (mitogen-activated protein kinase 7)
Diseases named in the same sentence as MAPK7 in open-access papers (continued):
Sharing a sentence is not in itself a finding about the gene and the disease.
coronary artery disease (4 papers, 2020 to 2023). "The elevated expression of DUSPs might explain the loss in protective MAPK7 signaling activity during coronary artery disease." (PMID 34493753, 2021). "In endothelial cells there is reciprocity between MAPK7 signaling and EZH2 expression and disturbances in this reciprocal signaling associate with the induction of EndMT and severity of human coronary artery disease." (PMID 34493753, 2021). "Dysregulation in the reciprocity between MAPK7 activation and EZH2 expression is associated to the induction of EndMT and the severity of coronary artery disease." (PMID 34493753, 2021). "Nonetheless, the expression of DUSP-1 is associated with an increasing IMT, and a decreased expression of MAPK7 in coronary artery disease." (PMID 34493753, 2021). "Disturbance in the reciprocity between MAPK7 and EZH2 result in the induction of EndMT and associate to the degree of human coronary artery disease." (PMID 34493753, 2021). "Collectively, these data suggest that in coronary artery disease, the reciprocity between MAPK7 activity and EZH2 expression is regulated by miR-101." (PMID 34493753, 2021). "Byambasuren revealed that miR-374b levels are elevated in human coronary artery disease and inversely correlate with MAPK7 expression, suggesting that the TGF–miR-374b–MAPK7 axis plays a key role in the induction of EMT during intimal hyperplasia and early lesions." (PMID 37373529, 2023). "Either preserving MAPK7-CEBPβ or directly impinging mir128-3p appears to be a potential approach to mitigate cardiac injury and could be an adjunctive treatment option in combination with surgical interventions for patients with ischemic heart disease." (PMID 32223896, 2020). "Using this approach, we show that there is a disbalance in MAPK7 activity and EZH2 expression in coronary artery disease and that this disbalance is perturbed with increasing IMT." (PMID 34493753, 2021). "Here, we report that in the endothelium there is reciprocity between MAPK7 and EZH2 in the regulation of EndMT and in human coronary artery disease." (PMID 34493753, 2021). "In human coronary artery disease, we assessed the expression levels of MAPK7 and EZH2 and found that with increasing intima/media thickness ratio, MAPK7 expression decreased, whereas EZH2 expression increased." (PMID 34493753, 2021). "In contrast, EZH2 expression is elevated in coronary artery disease and an increasing coronary artery intima-media thickness ratio associates with increased EZH2 expression (r2 = 0.4417, p = 0.004), suggesting reciprocity between MAPK7 and EZH2 in human coronary artery disease." (PMID 34493753, 2021). "Currently, it is elusive how the crosstalk between MAPK7 and EZH2 is regulated in the endothelium and whether the balance between MAPK7 and EZH2 is disturbed during intimal hyperplasia and coronary artery disease." (PMID 34493753, 2021). "Moreover, the expression level of miR-101 associates with MAPK7 (r2 = 0.4262, p = 0.005) and tends to associate to EZH2 (r2 = 0.2304, p = 0.051) in coronary artery disease, where a negative association between MAPK7 and EZH2 expression (r2 = 0.2568, p = 0.038) is present." (PMID 34493753, 2021). "Moreover, the increase in DUSP-1 expression associates with increased EZH2 expression in coronary artery disease (r2 = 0.4541, p = 0.0030) and the increase in DUSP-1 expression tends to associate with decreased MAPK7 expression (r2 = 0.1686, p = 0.1016), although not significantly." (PMID 34493753, 2021).
lymphoma (4 papers, 2011 to 2022). A malignant (clonal) proliferation of B- lymphocytes or T- lymphocytes which involves the lymph nodes, bone marrow and/or extranodal sites. "MAPK7 is deregulated in numerous types of cancer, including lymphoma." (PMID 27793024, 2016).
pulmonary fibrosis (4 papers, 2014 to 2025). Chronic progressive interstitial lung disorder characterized by the replacement of the lung tissue by connective tissue, leading to progressive dyspnea, respiratory failure, or right heart failure. "Inhibition of MAPK7 blocked the TGF-β1 signal for Smad3 transcriptional activity via acetylation and regulated TGF-β1-induced pulmonary fibrosis." (PMID 29084594, 2017).
esophageal cancer (3 papers, 2014 to 2024). A primary or metastatic malignant neoplasm involving the esophagus. "Taken together, our data provide the first reported incidences of dysregulated MAPK7 expression in clinical samples of squamous cell lung and esophageal carcinoma." (PMID 26040563, 2015).
medulloblastoma (3 papers, 2013 to 2019). A malignant, invasive embryonal neoplasm arising from the cerebellum. "Overexpression of MAPK7 has been shown to promote apoptotic cell death in medulloblastoma cell lines." (PMID 28596290, 2017).
psoriasis (3 papers, 2022 to 2025). An autoimmune condition characterized by red, well-delineated plaques with silvery scales that are usually on the extensor surfaces and scalp. "Subsequently, WGCNA showed the hub genes (e.g., S100A12, CYCS, NOD2, STAT1, HSPA4, AIM2, MAPK7), which were significantly associated with clinical phenotype, PANoptosis signature, and identified immune response in psoriasis." (PMID 38125299, 2024).
schizophrenia (3 papers, 2021 to 2024). A major psychotic disorder characterized by abnormalities in the perception or expression of reality. "Interestingly, other variants were found in hmsLRI-E connected to genes that had not been previously associated with schizophrenia (KIZ, CDKAP2, EPN2, MAPK7, B9D1)." (PMID 35887306, 2022).
COVID-19 (2 papers, 2022 to 2023). A disease caused by infection with severe acute respiratory syndrome coronavirus 2. "Mitogen-activated Protein Kinase 7 (MAP2K7) encodes for an augmenter of the c-Jun kinase pathway during T-cell activation and is elevated in severe COVID-19." (PMID 36143338, 2022). "In comparison to the COVID-19(-) PU controls, genes highly expressed in the TV group fell into categories that included neutrophil dysfunction (CD274, PADI2), inhibition of B and T cell responses (CD22, IRF4, ORAI1), and upregulation of pro-inflammatory response pathways (CARD8, MAPK7, IRF7, IFIH1)." (PMID 37026002, 2023).
metastatic prostate carcinoma (2 papers, 2009 to 2013). A carcinoma that arises from the prostate gland and has spread to other anatomic sites. "In addtion, the identified interactions in metastatic prostate cancer contain several experimentally confirmed targets of hsa-miR-143 and −145, including CLINT1, CDKN1A, IRS1, MAPK7, PPM1D and SOD2." (PMID 23782521, 2013).
squamous carcinomas (2 papers, 2015 to 2021). "Fluorescent in situ hybridization (FISH) analysis identified high level MAPK7 gene amplification in 4 % (3/74) of NSCLC (enriched to 6 % (3/49) in squamous cell carcinoma) and 2 % (2/95) of sqEC." (PMID 26040563, 2015). "Fluorescence in situ hybridization (FISH) analysis identified MAPK7 gene amplification in 4 % (3/74) of non-small cell lung cancers (NSCLC) (enriched to 6 % (3/49) in squamous cell carcinoma) and 2 % (2/95) of squamous esophageal cancers (sqEC)." (PMID 26040563, 2015).
acute lymphoblastic leukaemia (1 paper, 2015). "Interestingly however, oncogenic activity has been attributed to MEF2D fusion proteins in acute lymphoblastic leukaemia, underlining a broader role for MAPK7 signaling in oncogenesis." (PMID 26040563, 2015).
angiosarcoma (1 paper, 2025). A malignant tumor arising from the endothelial cells of the blood vessels. "However, this was based on a small sample size, and further studies would be helpful to further understand MAPK7’s role in angiosarcoma." (PMID 41301029, 2025). "MAPK7 is a driver of epithelial–mesenchymal transition, and its sole occurrence in primary tumors suggests that it might play a role in angiosarcoma progression and development." (PMID 41301029, 2025).
artery disease (1 paper, 2021). "In contrary artery disease—a condition associated with EndMT1,26—the reciprocity between MAPK7 and EZH2 is disturbed, resulting in elevated expression of DUSP-1 and EZH2 and the decreased expression of MAPK7." (PMID 34493753, 2021).
childhood cancer (1 paper, 2020). "The approach here finds that blockade of MAPK7/MMP9 signalling may overcome current hurdles for targeting pathways that ultimately lead to metastatic lung nodule formation in a childhood cancer." (PMID 32655131, 2020).
epilepsy (1 paper, 2017). A brain disorder characterized by episodes of abnormally increased neuronal discharge resulting in transient episodes of sensory or motor neurological dysfunction, or psychic dysfunction. "MAPK7 and MRAS are two proliferation-associated genes in our candidate epilepsy associated gene list." (PMID 28255556, 2017).
esophageal tumor (1 paper, 2015). "The data herein provide a first description of the identification of clinical squamous cell lung and esophageal tumor samples harbouring gene amplified and overexpressed MAPK7." (PMID 26040563, 2015).
Insulin resistance (1 paper, 2020). Increased resistance towards insulin, that is, diminished effectiveness of insulin in reducing blood glucose levels. "MAPK7 deficiency promotes cardiac insulin resistance and injury under hypoxic condition." (PMID 32223896, 2020).
Potocki-Lupski syndrome (1 paper, 2020). "MAPK7 is located in chromosome 17p11.2, where a 3.7-Mb duplication exists, which is considered the cause of Potocki-Lupski syndrome (PTLS; MIM #610883), a disease having approximately 70–90% comorbidity with ASD." (PMID 31838722, 2020).
rheumatoid arthritis (1 paper, 2021). A chronic, systemic autoimmune disorder characterized by inflammation in the synovial membranes and articular surfaces. "Our previous work has successfully shown that targeting MAPK at TNF receptor-associated factor 6-mitogen-activated protein kinase 7 (TRAF6-TAK1) signalosome in rheumatoid arthritis synovial fibroblasts using EGCG effectively curbs the IL-1 induced IL-6 production." (PMID 33668085, 2021).
Splenomegaly (1 paper, 2016). Abnormal increased size of the spleen. "Loss of Mapk7 in the hematopoietic compartment gives rise to extramedullary erythropoiesis, splenomegaly and an increased mutation rate in erythrocyte precursors, probably due to an imbalance of dNTPs." (PMID 27793024, 2016).
thymic lymphomas (1 paper, 2016). "To test this hypothesis, and as Atm−/− mice show a strong predisposition to thymic lymphomas, we eliminated MAPK7 in the hematopoietic system of Atm−/− mice and assessed the time of tumor appearance." (PMID 27793024, 2016).
uterine corpus endometrial carcinoma (1 paper, 2022). A endometrial carcinoma (disease) that involves the body of uterus. "Furthermore, analysis of the uterine corpus endometrial carcinoma database (TCGA, PanCancer Atlas), using the tool GEPIA2, showed a strong positive correlation between MAPK7 and NEMO/IKKγ mRNA expression levels." (PMID 36123565, 2022).
cancer (166 papers, 2007 to 2025). A tumor composed of atypical neoplastic, often pleomorphic cells that invade other tissues. "This is surprising as prior studies of different primary cancers, including ovarian and bone, have shown an association between MAPK7 mutations and metastasis." (PMID 41301029, 2025). "We focussed our evaluation of driver mechanisms underpinning our observations on the immunological effects of MAPK7 loss, as seen in other cancer models, and the interaction with MMP9 signalling therein." (PMID 32655131, 2020). "MAPK7 has been implicated in numerous types of cancer with pro-survival and pro-growth roles in tumor cells, but its functional relation with tumor suppressors is not clear." (PMID 27793024, 2016). "The results indicate that there is not a statistically significant relationship between the presence of ATM mutations and MAPK7 mRNA content in human cancer." (PMID 27793024, 2016). "To test this hypothesis, we queried The Cancer Genome Atlas (TCGA) clinical database for the expression of MAPK7 mRNA in human cancers presenting mutated ATM." (PMID 27793024, 2016). "MAP2K5 activates MAPK7 that, in combination with MMP9, is associated with positive tumor-inducing signaling in cancer patients." (PMID 36552714, 2022). "A bioinformatics analysis through TIMER online web tool with default settings showed significantly increased messenger (m)RNA levels of CCNB1/CDC42/MAPK7/CD44 in pan cancers, including GBM tumor tissues compared to normal tissues from TCGA)." (PMID 35008426, 2022). "We identified significantly increased mRNA levels of the CCNB1/CDC42/MAPK7/CD44 oncogenes in pan cancers, including GBM tumor tissues compared to normal tissues from TCGA, using the TIMER bioinformatics tool." (PMID 35008426, 2022). "Negative regulation of BAK by MAPK7/BMK1 phosphorylation at Y108 has been reported in several cancer cell lines." (PMID 33668112, 2021). "Consistently, cancer cells displaying elevated ERK5 expression due to MAPK7 amplification were insensitive to MEK5 inhibition or ERK5 downregulation by siRNA." (PMID 30901834, 2019). "Because of the involvement of MAP2K5/MAPK7 in angiogenesis, the epithelial-mesenchymal transition, and diverse oncogenic pathways, the role of MAP2K5/MAPK7 in cancer has been the subject of intense investigation for the last decade." (PMID 28596290, 2017). "Despite being the least well studied of the MAPK-modules, evidence supports a role for MAPK7-signaling in the pathology of several cancer types." (PMID 26040563, 2015). "However, the publishedstudies exploring chemically induced degradation of ERK5 protein castfurther doubt on ERK5 having a major role in driving cancer cell proliferation,in contrast to studies that examined gene silencing of MAPK7 with siRNA." (PMID 37002872, 2023). "In a variety of cancer cells, MAPK7 has been reported to negatively regulate the expression of P21." (PMID 32944217, 2020). "MAPK7 is mutated in a large variety of human cancers, although activating mutations of ERK5 have not been reported." (PMID 32023850, 2020). "Therefore, the prospect of using functional data (i.e. MAPK7 activity) will provide a closer view to the MAPK7 - ATM relationship in human cancer." (PMID 27793024, 2016). "In an attempt to confirm that the development of cancer in absence of Atm is favoured by MAPK7 function, we examined the MAPK7 mRNA content in human cancers presenting ATM mutations." (PMID 27793024, 2016). "We focused on the inhibition of Erk5 (MAPK7) since Erk5 is an attractive target for cancer therapy." (PMID 24762669, 2014). "By using the similar approach, inhibition of MAPK7, an essential MEK gene, attenuated the re-activation of MAPK signaling following long-term MEK inhibition in KRAS mutant cancer cells, suggesting that targeting MAPK7 may attenuate acquired resistance to MEK inhibition." (PMID 35372044, 2022).
cancer (continued). "In silico data analysis of 32 types of cancers in 10,953 patients (data from TCGA PanCancer Atlas Studies available from the cBioPortal) allowed us to establish that none of the reported MAPK7 missense mutations is involved in ERK5 SUMOylation or is located in the TEY motif." (PMID 32023850, 2020). "Macrophages, especially those with a proinflammatory phenotype (e.g., M1), secrete cytokines and inflammatory mediators that can activate signaling pathways in cancer cells and the TME, including Mapk7." (PMID 40942182, 2025). "In pan-cancer analysis, SHOX2 expression positive correlated with CDKN2C (R = 0.41), COL6A1 (R = 0.35), COL6A2 (R = 0.37), DCHS1 (R = 0.37), MAPK7 (R = 0.34), PRRX1 (R = 0.37), RAB23 (R = 0.36) and RSRC1 (R = 0.36) via GEPIA2." (PMID 37170390, 2023). "In contrast with these reports, another study showed that ERK5 is dispensable for proliferation of cancer cells, including CRC cells, displaying MAPK7 amplification." (PMID 30901834, 2019). "GEPIA2 database analysis of 33 cancer types showed the following top 10 ALKBH5-related genes: GID4 (R=0.71), TOP3A (R=0.67), MAPK7 (R=0.66), NT5M (R=0.61), FLII (R=0.59), ZNF18 (R=0.57), DRG2 (R=0.57), COPS3 (R=0.56), MED9 (R=0.56) and PRPSAP2 (R=0.56) (all P<0.0001)." (PMID 35444654, 2022). "In this study, it was showed that the treatment of miR-200b could target AP-2α/MAPK7 in CCA xenografts models in order to interfere the regulatory loop involving miR-200b and TGF-β to repress EMT for cancer metastasis." (PMID 29084594, 2017). "Further, miR-200b could target transcription factors, AP-2 alpha (TFAP2A), and MAPK7, which, in turn, inhibit the expression of TGF-β, impair TGF-β-induced EMT and decrease cancer cell proliferation in vitro." (PMID 29084594, 2017). "The aim of this study was to identify molecular gene signatures, responsible for cancer initiation, progression, resistances and to treatment, metastasis, and also evaluate the potency of our novel compounds SJ10 as potential target for CCNB1/CDC42/MAPK7/CD44 oncogenic signatures." (PMID 35008426, 2022). "Notably, the suppression of their common target KLF4 could inhibit the expression of various Erk5 (mitogen-activated protein kinase 7) targets and further affect the MAPK cascade in the regulation of endothelial integrity in cancer." (PMID 26692821, 2015).